Y_RNA (Y RNA )
Gene: Miscellaneous RNA gene on chromosome X (94,178,005 to 94,178,106, forward strand). Ensembl gene ENSG00000202410.
Homologues: Orthologues: chimpanzee Y_RNA (100% identical), macaque Y_RNA (92% identical), guinea pig Y_RNA (84% identical). Paralogues in human: Y_RNA (82% identical), Y_RNA (81% identical), RNY3 (80% identical), Y_RNA (80% identical), RNY3P2 (79% identical), Y_RNA (79% identical), Y_RNA (78% identical), RNY3P1 (77% identical), Y_RNA (77% identical), RNY3P13 (76% identical), RNY3P16 (76% identical), RNY3P4 (76% identical), and 93 more.